HELT (helt bHLH transcription factor)
Description:
Transcriptional repressor which binds preferentially to the canonical E box sequence 5'-CACGCG-3'.
Synonyms: HESL; HCM1228; Mgn; bHLHb44; MEGANE
Tractability: No criterion of Open Targets' tractability assessment is met for any kind of drug.
Gene: Protein-coding gene on chromosome 4 (185,018,490 to 185,020,953, forward strand). Ensembl gene ENSG00000187821.
Subcellular location: Nucleus
Gene Ontology:
Molecular function: DNA-binding transcription factor activity, RNA polymerase II-specific; RNA polymerase II cis-regulatory region sequence-specific DNA binding; DNA binding; DNA-binding transcription factor activity; DNA-binding transcription repressor activity, RNA polymerase II-specific; identical protein binding; protein dimerization activity
Biological process: anterior/posterior pattern specification; negative regulation of transcription by RNA polymerase II; Notch signaling pathway; regulation of neurogenesis; regulation of DNA-templated transcription
Cellular component: chromatin; nucleus; transcription regulator complex
Genetic constraint (gnomAD): Loss-of-function variants: 9 observed, 18.32 expected, observed/expected ratio (o/e) 0.49, 90% interval 0.29 to 0.86. The upper end of that interval is the gene's LOEUF score, 0.86, which puts it in group 3 of 6, group 1 being the genes least tolerant of losing a copy. Missense variants: 366 observed, 321.79 expected, observed/expected ratio (o/e) 1.14, 90% interval 1.04 to 1.24. Synonymous variants: 162 observed, 145.08 expected, observed/expected ratio (o/e) 1.12, 90% interval 0.98 to 1.27.
Homologues: Orthologues: chimpanzee HELT (100% identical), macaque HELT (99% identical), rabbit HELT (96% identical), pig HELT (94% identical), dog HELT (94% identical), guinea pig HELT (93% identical), mouse Helt (92% identical), rat Helt (90% identical), zebrafish helt (68% identical), tropical clawed frog helt (67% identical), Drosophila melanogaster cwo (20% identical), Drosophila melanogaster E(spl)m3-HLH (15% identical), and 7 more. Paralogues in human: HEY2 (31% identical), HEY1 (30% identical), HEYL (29% identical), HES1 (22% identical), BHLHE40 (21% identical), BHLHE41 (21% identical), HES4 (19% identical), HES6 (18% identical), HES2 (17% identical), HES3 (17% identical), HES7 (17% identical), HES5 (14% identical).
Diseases named in the same sentence as HELT in open-access papers:
HELT is named in the same sentence as 5 diseases in open-access papers, as found by Europe PMC text mining. Sharing a sentence is not in itself a finding about the gene and the disease.
HELT shares sentences with these, for which no sentence is quoted: adenoma (1 paper); cancer (1); eosinophilic disorders (1); ovarian adenocarcinoma (1); ovarian carcinoma (1).